CCL3 (C-C motif chemokine ligand 3)
Diseases named in the same sentence as CCL3 in open-access papers (continued):
Sharing a sentence is not in itself a finding about the gene and the disease.
adenoma (3 papers, 2022 to 2024). A neoplasm arising from the epithelium. "This notion is substantiated by CCL19 downregulation in adenomas with high-grade dysplasia and by an inverse association of CCL3 with polyp size and of CCL4 with number of polyps." (PMID 38338661, 2024). "Consistent with an observation on gene elevation in inflammatory hyperplasia, CCL3 was upregulated in hyperplastic polyps and downregulated in classic adenomas." (PMID 38338661, 2024). "In adenomas, only CCL4 was expressed at comparable level between the lesion and paired normal mucosa, while the expression of CCL3 (p = 0.006), CXCL2 (p = 0.023) and CCL19 (p = 0.016) was significantly higher in lesions." (PMID 38338661, 2024). "The individual analysis of polyps with adenocarcinomas (AC) and precancerous lesions of classic adenoma (A) and alternative serrated (H) transformation pathways showed opposite trends in serrated (upregulation) and classic (downregulation) pathways, significant for CCL3 and non-significant for CCL4." (PMID 38338661, 2024).
amyloid (3 papers, 2020 to 2021). "To assess whether the increased amyloid plaque burden resulted in an exacerbation of pro-inflammatory responses, we measured levels of the inflammation-associated molecules CXCL1, CCL3, IL-33, TNFα, IL-6, and IL-1β by multiplexed MSD ELISA." (PMID 32943069, 2020).
atrial fibrillation (3 papers, 2018 to 2024). A disorder characterized by an electrocardiographic finding of a supraventricular arrhythmia characterized by the replacement of consistent P waves by rapid oscillations or fibrillatory waves that vary in size, shape and timing and are accompanied by an irregular ventricular response. "Conversely, lower levels of CCL3, IL-12, IL-5, IL-10, IL-13 were observed in the ZIKV-infected patient with atrial fibrillation as compared to the healthy controls." (PMID 29370812, 2018).
B cell lymphoma (3 papers, 2017 to 2020). "Large amounts of CCL3 and CCL4 accumulated in the culture medium of EBNA2-expressing cell lines (BJAB, U2932, DG75, and Toledo) and primary B cell lymphoma cells." (PMID 28036258, 2017). "Moreover, evaluation of the CCL3 and CCL4 levels may be helpful for selecting B-cell lymphoma patients likely to benefit from doxorubicin treatment in combination with the velcade or ibrutinib." (PMID 33146700, 2020).
brain injury (3 papers, 2017 to 2024). Acute and chronic (see also brain INJURIES, CHRONIC) injuries to the brain, including the cerebral hemispheres, CEREBELLUM, and brain STEM. "CCL-3, also known as Macrophage Inflammatory Protein 1-α, is primarily secreted by astrocytes, microglia, endothelial cells, and neurons and has been found to be upregulated in the CSF of patients after traumatic brain injury." (PMID 29228970, 2017).
chorioamnionitis (3 papers, 2012 to 2023). A morphologic finding indicating inflammation of the fetal sac membranes. "Ccl2 and Ccl3 code for known inflammatory chemokines that are elevated in chorioamnionitis-exposed preterm infants." (PMID 38481391, 2023).
colon adenocarcinoma (3 papers, 2021 to 2026). "In colon adenocarcinoma (COAD), heightened CCL3 levels in both TAMs and tumor cells, acting via the CCL3-CCR5 axis, boost Akt-mediated migration and invasiveness." (PMID 40191202, 2025).
colorectal adenocarcinoma (3 papers, 2021 to 2024). The most common type of colorectal carcinoma. "CCL3 interacts with CCR5 and can promote the movement and infiltration of colorectal adenocarcinoma cells." (PMID 39334887, 2024).
colorectal tumor (3 papers, 2021 to 2025). "The in vitro investigation used murine colorectal tumor cell lines (CT26 and MC38) that stably overexpressed different chemokines, including CCL3, established by lentiviral transduction." (PMID 41153795, 2025). "Murine colorectal tumor cell lines (CT26 and MC38) stably overexpressing mouse C-C motif chemokine ligand 3 (CCL3), CCL19, CCL21, and X-C motif chemokine ligand 1 (XCL1) were established by lentiviral transduction." (PMID 36654820, 2022).
congestive heart failure (3 papers, 2015 to 2021). Failure of the heart to pump a sufficient amount of blood to meet the needs of the body tissues, resulting in tissue congestion and edema. "In fact, many factors such as CCL-2, CCL-3, and CCL-5, whose gene expression was highly increased in preconditioned MSCs, were reported to be upregulated in patients with structural remodeling including hypertrophy and congestive heart disease." (PMID 33927770, 2021).
Gaucher disease (3 papers, 2018 to 2020). Gaucher disease (GD) is a lysosomal storage disorder encompassing three main forms (types 1, 2 and 3), a fetal form and a variant with cardiac involvement (Gaucher disease - ophthalmoplegia - cardiovascular calcification or Gaucher-like disease). "Increased expression of Ccl3 and Ccl4 in the brain and cerebellum were also observed in different lysosomal storage diseases such as MPSIIIA and MPSIIIB, and Gaucher disease." (PMID 32951593, 2020).
glaucoma (3 papers, 2012 to 2021). Increased pressure in the eyeball due to obstruction of the outflow of aqueous humor. "IL-4, IL-5, CCL3, and G-CSF was detected in less than 50% of samples in both control and glaucoma groups and therefore were not included in further analysis." (PMID 22355254, 2012).
Hemophagocytic lymphohistiocytosis (3 papers, 2010 to 2021). "In addition, CCL3 has been localized to EC of blood vessels and splenic sinusoids in the hemophagocytic syndrome." (PMID 20047691, 2010).
interstitial lung disease (3 papers, 2011 to 2017). A diverse group of lung diseases that affect the lung parenchyma. "Specifically, Oshima and associates using a cohort of pulmonary sarcoidosis patients (n = 17) found that the expression of CCL3 from BALF cell pellets was elevated as compared to other interstitial lung diseases (n = 10)." (PMID 21463523, 2011).
intervertebral disc degeneration (3 papers, 2024 to 2025). "Moreover, CCL3 has been associated with intervertebral disk degeneration." (PMID 40649738, 2025). "These indicate that Galectin-3 can affect the expression of CCL3, may play a role in the inflammatory cell infiltration of the intervertebral disc cartilage endplate, and affect the occurrence of intervertebral disc degeneration." (PMID 38561725, 2024).
leukocytosis (3 papers, 2017 to 2026). "Leukocytosis was decreased in infected ccl3−/− mice, paralleling the accumulation of CD8+ T cells devoid of activated CCR5+ LFA-1+ cells in the spleen." (PMID 32194558, 2020).
liver cirrhosis (3 papers, 2017 to 2025). "Patients with liver cirrhosis often exhibit increased levels of CCL5, along with related chemokines CCL3 and CCL4." (PMID 38338668, 2024). "CXCL10, CXCL11, CCL3, CCL4 and liver cirrhosis were the predictive factors for non-NR by univariate logistic analysis, but only the CCL4 was the independent predictor for non-NR by multivariate logistic analysis." (PMID 29284412, 2017). "By univariate logistic regression analysis, rs12979860 CC genotype, CXCL10, CXCL11, CCL3, CCL4 and liver cirrhosis were the factors for non-NR." (PMID 29284412, 2017).
nasopharyngeal carcinoma (3 papers, 2018 to 2025). A carcinoma arising from the nasopharyngeal epithelium. "Nasopharyngeal carcinoma (NPC) is a neoplasm related to inflammation; the expression of cytokines, such as CCL3, CCL4, CCL20, IL-1α, IL-1β, IL-6, IL-8, and IL-10, among others, is presumed to be associated with NPC occurrence and development." (PMID 39483474, 2024).
Peri-Implantitis (3 papers, 2018 to 2023). An inflammatory process with loss of supporting bone in the tissues surrounding functioning DENTAL IMPLANTS. "During the treatment of peri-implant mucositis and peri-implantitis there were minimal effects of non-surgical treatment alone on the investigated inflammatory biomarkers (IL-4, IL-10, and IL-12, TNF-a, RANKL, OPG IL-1β, IL-6, TNF-α, MCP-1/CCL2, MIP-1α/CCL3, IFN-γ, MMP-8, sRANKL, OPG and G-CSF)." (PMID 36360962, 2022).
peripheral nerve injury (3 papers, 2011 to 2019). Injury to a peripheral nerve. "After SCI, Ccl3 were induced significantly in the dorsal horns 2 days after lesion and remained at high levels with significantly higher intensities, while, after peripheral nerve injury, Ccl3 and their receptors (CCR2 and CCR1/CCR5, resp)." (PMID 29164149, 2017). "Consistent with that possibility, the chemokines CCL2, CCL3, and CX3CL1 are all highly expressed after peripheral nerve injury with the corresponding chemokine receptors, CCR2, CCR5, and CX3CR1 expressed by NK cells." (PMID 30712871, 2019).
prostate tumor (3 papers, 2020 to 2023). "In our dataset, we observed high expression of CXCL12 in fibroblasts, CCL2 in pericytes, and CCL3,4, and 5 in epithelial and tumor cells, suggesting a potential role of fibroblasts and pericytes in recruiting monocytes to the prostate tumor." (PMID 36750562, 2023). "Strikingly, CCL3 and CCL4 also comprise 2 of the immune genes with reproducibly increased expression in BL compared with WH prostate tumors, a finding replicated in multiple independent array-based studies but conspicuously absent from RNA-Seq–based studies such as TCGA." (PMID 36752203, 2023).
rectal cancer (3 papers, 2021 to 2025). A primary or metastatic malignant neoplasm that affects the rectum. "In their population-based case–cohort study, plasma CCL3 levels were inversely associated with colon and rectal cancer risk." (PMID 41153795, 2025).
retinitis pigmentosa (3 papers, 2015 to 2016). Retinitis pigmentosa (RP) is an inherited retinal dystrophy leading to progressive loss of the photoreceptors and retinal pigment epithelium and resulting in blindness usually after several decades. "In the retina, deficiencies in Ccl3 reduce progressive photoreceptor death and monocyte recruitment in degenerative Abca4−/− Rdh8−/− mice, and in the Mertk−/− mouse model of retinitis pigmentosa." (PMID 25595590, 2015). "Ccl3 is implicated in animal models of AMD/Stargardt disease (Abca4−/−Rdh8−/−), retinitis pigmentosa (Mertk−/−), and oxygen-induced retinopathy." (PMID 26911327, 2016).
RSV bronchiolitis (3 papers, 2014 to 2022). "Among the most abundant chemokines in infants suffering from RSV bronchiolitis are CXCL10/IP-10, CXCL8/IL-8, CCL2/MCP-1 and CCL3/MIP-1α." (PMID 34320038, 2021).
Salmonella Infections (3 papers, 2019 to 2023). Infections with bacteria of the genus SALMONELLA. "It is well known that Mφ play an essential role in the host response to Salmonella infection, and that the chemokine CCL3 is critical in the regulation and recruitment of leukocytes (i.e., Mφ and PMN)." (PMID 31412039, 2019). "It is likely that when gut-resident Mφ fail to contain the Salmonella infection they release cytokines/chemokines (e. g., IL-6, IL-8, TNF-α, and CCL3) to attract more macrophages and PMN to the diseased area." (PMID 31412039, 2019). "Chemokines such as CCL3 serve as PMN attractors to the site of infection, and have protective roles in Salmonella infections." (PMID 31412039, 2019).
Stargardt disease (3 papers, 2015 to 2025). "Studies have also indicated that in mouse models of Stargardt disease and RP, retinal microglia-produced CCL3 (MIP-1α) can worsen inflammation and degeneration." (PMID 40519267, 2025).
steatosis (3 papers, 2022 to 2026). Increased lipid within the cytoplasm of cells. "Surprisingly, CCL3 therapy improved hepatocyte steatosis and ballooning while lowering ALT levels." (PMID 41597195, 2026). "The plasma level of NT‐3, CCL20, CCL4, CCL3, LIF‐R, OPG, and HGF was higher, and SCF was lower only in the severe steatosis versus no steatosis." (PMID 35128832, 2022).
systemic inflammatory response syndrome (3 papers, 2019 to 2022). SIRS is a serious condition related to systemic inflammation, organ dysfunction, and organ failure. "The CD49d+CD11b− N1 neutrophils isolated from SCIDbg mice with mild systemic inflammatory response syndrome (SIRS) secrete the cytokine IL-12 and chemokine CCL3, while CD49d−CD11b+ N2 neutrophils isolated from SCIDbg mice with severe SIRS mainly produce IL-10 and CCL2." (PMID 31727175, 2019).
systemic sclerosis (3 papers, 2013 to 2021). A chronic disorder, possibly autoimmune, marked by excessive production of collagen which results in hardening and thickening of body tissues. "Similarly, in systemic sclerosis (skin fibrosis), the levels of circulating CCL2, CCL3, and CCL5 chemokines were significantly higher in patients with systemic sclerosis than in controls." (PMID 33519923, 2020). "MIP-1α (CCL3) is a non-neutrophil inflammatory cell migration factor that was increased in BALF from IPF patients, and its serum level has been associated with the onset of ILD in systemic sclerosis." (PMID 34158044, 2021).
vitamin D deficiency (3 papers, 2014 to 2021). A nutritional condition produced by a deficiency of VITAMIN D in the diet, insufficient production of vitamin D in the skin, inadequate absorption of vitamin D from the diet, or abnormal conversion of vitamin D to its bioactive metabolites. "Vitamin D deficiency was linked to the reduction of such chemokines as MIP-1α (CCL3) and IL-8 (CXCL8)." (PMID 34698104, 2021). "Vitamin D deficiency significantly enhanced the basal expression of IL-1β, IL-6, and TNF-α in the lungs of mice, while did not influence the basal expression of CXCL1 and CCL3." (PMID 24926881, 2014).
abdominal aortic aneurysm (2 papers, 2024). Enlargement and ballooning of the vessel that supplies arterial blood to the abdomen, pelvis and legs. "We obtained six macrophage hub genes (IL-1B, CXCL1, SOCS3, SLC2A3, G0S2, and CCL3) that can effectively diagnose abdominal aortic aneurysm." (PMID 38867262, 2024). "In a preclinical abdominal aortic aneurysm model induced by CaCl2, an increased expression of CCL3 was observed." (PMID 38709145, 2024).
acute GVHD (2 papers, 2013 to 2024). "In a murine model of acute GVHD, blockade of PI3Kγ resulted in a reduction in the expression of pro-inflammatory chemokines, namely CCL3 and CCL5." (PMID 39840040, 2024). "Similarly, elevated levels of CCL2, CCL3, and CCL5 in the liver and intestines of acute GVHD mice mediate the infiltration of neutrophils and activated T cells." (PMID 39840040, 2024).
alcoholic hepatitis (2 papers, 2016 to 2020). Acute hepatitis resulting from ingestion of alcohol. "In contrast to human data where Ccl2, Ccl3, Ccl20 and Cxcl10 transcripts were significantly changed in alcoholic hepatitis compared to healthy control, none of these statistically significant changes were found in the murine models." (PMID 32051453, 2020).
aneurysm (2 papers, 2015 to 2020). Bulging or ballooning in an area of an artery secondary to arterial wall weakening. "The analysis using BM chimeric mice revealed that aneurysm formation and MMP-9 expression were enhanced by CCL3 deficiency restricted to BM-derived cells." (PMID 33239616, 2020). "Hence, we examined the in vivo effects of an MMP-9 inhibitor on aneurysm formation in WT, CCl3−/− and Ccr5−/− mice after CaCl2 treatment." (PMID 33239616, 2020). "Moreover, we examined in vivo effects of a specific CCR5 antagonist, maraviroc, on aneurysm formation in WT and Ccl3−/− mice." (PMID 33239616, 2020). "Thus, it is reasonable to examine the therapeutic activity of CCL3 for an aneurysm." (PMID 33239616, 2020). "Thus, macrophages could produce CCL3 after migrating into CaCl2-induced aneurysm lesions but might lose a capacity to express CCL3 when they became apoptotic." (PMID 33239616, 2020). "Furthermore, given that CCL3 or its derivatives have been tried in humans to induce hematopoietic cell mobilization to peripheral blood, without severe adverse effects, it may be a therapeutic strategy for an aneurysm." (PMID 33239616, 2020). "However, maraviroc treatment failed to have any effects on CaCl2-induced aneurysm formation in Ccl3−/− mice." (PMID 33239616, 2020).
aortic aneurysm (2 papers, 2020 to 2022). A ruptured aneurysm located in the wall of the proximal portion of the descending aorta proceeding from the arch of the aorta. "We next examined intra-aortic gene expression of MMPs and TIMPs, which are presumed to be involved in aortic aneurysm formation and observed that Ccl3−/− mice exhibited significantly enhanced intra-aortic Mmp9 mRNA expression compared with WT mice." (PMID 33239616, 2020).
autism (2 papers, 2022). Persistent deficits in social interaction and communication and interaction as well as a markedly restricted repertoire of activity and interest as well as repetitive patterns of behavior. "The current study demonstrated that PPA-induced autism in rats was characterized by a significant increase in the expression of TNF-α, IL-6, IL-17, CCL-3, CCL-5, and CXCL-16 levels as a down-regulation of OPG in the brain of PPA-induced autism-like rats, compared to the control animals." (PMID 35334937, 2022).
bacterial vaginosis (2 papers, 2011 to 2023). Infection caused by bacterial overgrowth in the vagina. "Indeed, bacterial vaginosis has been associated with increased levels of IL-1 beta, IL-6, IL-8, IL-10 and TNF-alpha, RANTES (CCL5), macrophage inflammatory protein (MIP-1 alpha/CCL3) and MIP-1 beta (CCL4) in genital samples." (PMID 21966450, 2011).
brain infarction (2 papers, 2021 to 2023). Tissue necrosis in any area of the brain, including the cerebral hemispheres, the cerebellum, and the brain stem. "Ccl3 can also exacerbate brain infarction in the cortical region in MCAO." (PMID 37234258, 2023).
brucellosis (2 papers, 2024 to 2025). Brucellosis is a bacterial infection that spreads from animals to people via unpasteurized dairy products or by exposure to contaminated animal products or infected animals. "As the major contributor of potential inflammatory storm, many inflammatory response genes (e.g., ITGB2, OSM, FPR1, CEBPB, NINJ1) and canonical pro‐inflammatory cytokines (e.g., CXCL8, CCL3, CCL4, TNF, IL1B, S100A12) were expressed at higher levels in brucellosis patients than in healthy donors." (PMID 39135683, 2024). "Procarta cytokine analysis from the plasma of these individuals, supported the finding that brucellosis patients, especially for acute patients, had a higher level of multiple pro‐inflammatory cytokines, such as CXCL8/IL8, CCL3/MIP‐α, CCL4/MIP‐β, TNF/TNF‐α, IL1B/IL1‐β." (PMID 39135683, 2024).
carcinoma in situ (2 papers, 2015 to 2017). "In contrast, CCL3-/- mice treated with 4NQO presented lesions with a lower grade of cellular atypia and severity, with 57% of the lesions graded as moderate and severe dysplasia (scores of 2 and 3, respectively) and 43% classified as carcinoma in situ." (PMID 28881626, 2017).
cervical cancer (2 papers, 2021 to 2026). A primary or metastatic malignant neoplasm involving the cervix. "However, the role of CCL3 and CCL5 in cervical cancer needs to be further explored." (PMID 34830895, 2021).
chronic hepatitis C (2 papers, 2014 to 2017). "Importantly, the intrahepatic levels of the CCR5 ligands CCL3, 4 and 5 are increased in chronic hepatitis C." (PMID 24646914, 2014). "During chronic hepatitis C, the intrahepatic expression of the CCR5 ligands CCL3, 4 and 5 is increased." (PMID 24646914, 2014). "Furthermore, CCL3, CCL4, CCL5, CXCL9, CXCL10 and CXCL11 were found to increase in both liver and peripheral blood during chronic hepatitis C in several studies." (PMID 29284412, 2017).
corneal infection (2 papers, 2018 to 2024). A viral or bacterial infectious process affecting the cornea. "In a mouse model of Pseudomonas aeruginosa-induced corneal infection, antibodies directed against CCL2 or CCL3 significantly reduced neutrophil infiltration into the cornea and decreased corneal damage." (PMID 29661181, 2018).
cryptogenic fibrosing alveolitis (2 papers, 2016 to 2020). "It has been reported that in HTLV-1 positive cryptogenic fibrosing alveolitis (CFA) patients, a chronic inflammatory interstitial lung disease, the BALF levels of CCL3 and CXCL10, T cell chemoattractants and activators, are higher than those of without HTLV-1 infection." (PMID 32231656, 2020).